PDCD1 (programmed cell death 1)
Diseases named in the same sentence as PDCD1 in open-access papers (continued):
Sharing a sentence is not in itself a finding about the gene and the disease.
tumor (continued). "Although CHI (including PDCD1 blockade or anti-CTLA4) in patients with dMMR/MSI-H mCRC significantly increase the antitumor activity of tumor specific CD8+ T-cells with highly durable tumor response, they are associated with virtually no activity in patients with pMMR/non-MSI-H mCRC." (PMID 33240813, 2020). "The overexpression of FASLG and PDCD-1 mRNAs in the cell lysates could be related to the tumor immune privilege, as is the case in many other carcinomas." (PMID 33202950, 2020). "Interestingly, in basal and squamous cell carcinomas of the skin, programmed cell death-1 (PD-1) blockade upregulated the expression of several effector genes in tumor-infiltrating MAIT cells." (PMID 32849590, 2020). "Recently, immune checkpoint blocker therapy, particularly antibodies targeting the programmed cell death-1 (PD-1)/programmed cell death ligand-1 (PD-L1) pathway, has sparked a boom in systemic treatment aimed at improving the tumor response and survival of HCC patients." (PMID 33488622, 2020). "Moreover, hypoxia counteracts the desired effects of CHI, such as PDCD1 or CTLA4 inhibitors leading to CHI resistance of tumor cells." (PMID 33240813, 2020). "Cytotoxic T lymphocyte antigen-4 (CTLA-4) receptor, programmed cell death-1 (PD-1) receptor, both expressed on the T cell surface, and the PD-1 ligands, PD-L1/L2, expressed on the APCs and the tumor cell surface, represent potential targets of the novel immuno-checkpoint inhibitors." (PMID 32899891, 2020). "Despite the unprecedented tumor regression and long‐term survival benefit observed with agents against programmed cell death 1 (PD‐1) or programmed cell death 1 ligand (PD‐L1), a large portion of patients do not benefit and many responders eventually relapse (Kim, Herbst, & Chen, 2018)." (PMID 31493351, 2019). "Therapies targeting the programmed cell death-1 (PD-1), programmed cell death ligand-1 (PD-L1) and cytotoxic T-lymphocyte-associated antigen-4 (CTLA-4) immune checkpoints have received approval across a wide range of tumor types, including NSCLC." (PMID 31871778, 2019). "Following greater understanding of the multiple tumor immune escape mechanisms in recent years, programmed cell death 1/programmed cell death 1 ligand 1 (PD-1/PD-L1) pathway inhibition, followed by immune system tumor killing effect reactivation has become a new strategy for treating cancer." (PMID 29484143, 2018). "Tumor CD274 expression is a potential biomarker of a better response to anti-PDCD1/CD274 therapies." (PMID 29361689, 2018). "Programmed cell death ligand 1 (PD-L1, also known as B7-H1 or CD274) is believed to mediate local immune evasion in many types of cancer by binding to programmed cell death 1 (PD-1), its co-stimulatory receptor on T cells, to induce saturation of activated anti-tumor T cells." (PMID 29291717, 2018). "We wanted to test whether ablating Pdcd1 specifically in CAR T cells would allow for generation of tumor-specific cells with enhanced anti-tumor functionality." (PMID 28389661, 2017). "We hypothesized that genetic disruption of Pdcd1 in CAR T cells might be sufficient to rescue the observed impairment of anti-tumor activity against PD-L1+ cancer cells." (PMID 28389661, 2017). "In this study we tested whether Cas9 RNP mediated disruption of the endogenous Pdcd1 locus in primary human CAR T cells enhances anti-tumor efficacy." (PMID 28389661, 2017). "Ablation of Pdcd1 specifically in CAR T cells might therefore provide a safer way to overcome tumor immunosuppression, particularly when combined with TCR disruption to prevent activation of autoreactive T cells." (PMID 28389661, 2017). "Furthermore, PDCD1 methylation was shown to be associated with a HPV+ status, suggesting a major role of the PD-1 driven adaptive immune resistance in this tumor subgroup." (PMID 28487502, 2017).
tumor (continued). "For example, the enhanced anti-tumor functionality of Pdcd1 edited CAR T cells might allow physicians to administer fewer cells to achieve equivalent therapeutic effects." (PMID 28389661, 2017). "Furthermore, blockade of co-inhibitory molecules of TIGIT and programmed cell death-1 (PD-1) disrupts immune checkpoints and enhances anti-tumor activity." (PMID 26735971, 2016). "However, the IR tumours also had high expression of the negative regulators of immune response PDCD1 (PD-1), CD274 (PD-L1) and CTLA4 (CTLA-4)." (PMID 26729235, 2016). "During the past two decades, several studies of cancer immune escape revealed that one of the most important components of the underlying mechanism is an immunosuppressive co-signal (immune checkpoint) mediated by programmed cell death-1 (PD-1)/PD-1 ligand 1 (PD-L1) in the tumor microenvironment." (PMID 26899259, 2016). "For example, recent studies indicate that mismatch repair deficient tumours respond to immune checkpoint anti-programmed cell death 1 inhibitors in contrast to mismatch repair proficient tumours which showed no response." (PMID 27341022, 2016). "Indeed, we found that in mice bearing high tumour load and a high number of circulating PDCD1+ CTLs, blocking the PDCD1/PD-L inhibitory pathway resulted in enhanced clearance of the tumour cells." (PMID 25940792, 2015). "As CLL cells could directly trigger the appearance of T cells exhibiting an exhausted phenotype, we analysed if the number of PDCD1-expressing T cells correlated with the tumour volume in each of the lymphoid organs examined." (PMID 25940792, 2015). "We next assessed the expression of the ligands for PDCD1 on the surface of tumour cells in mice." (PMID 25940792, 2015). "Immune-checkpoint blockade (ICB) drugs such as antibodies against programmed cell death 1 (PD-1), programmed death ligand 1 (PD-L1) or cytotoxic T-lymphocyte-associated antigen 4 (CTLA-4) (respectively, anti-PD-1, anti-PD-L1 and anti-CTLA-4) aim to reinvigorate tumour-infiltrating CD8+ T cells." (PMID 40065102, 2025). "Additionally, correlations between CD68 expression and six TIICs (B cells, CD4+ T cells, CD8+ T cells, macrophages, NK cells, and cancer-associated fibroblasts) or four common TICs (PDCD1, CTLA4, IDO1, and CD40) were assessed using the Tumor Immune Estimation Resource (TIMER)." (PMID 40918116, 2025). "Notably, PDE2A expression was positively correlated with PDCD1 in most tumor tissues." (PMID 39699377, 2024). "In addition, the expression of programmed death ligand 1 (PD-L1) in tumor cells is regarded as a predictive marker for the response of the tumor to immunomodulatory therapies that target the programmed cell death 1 (PD-1)/PD-L1 pathway, with PD-L1 staining being diffusely positive in cases of EIMS." (PMID 39703852, 2024). "Thus, a gene expression profile associated to PDCD1/LAG3 could be extracted from tumors which indicated immune dysfunctionality, possibly from tumor-infiltrating T-cells." (PMID 39030301, 2024). "Additionally, CRISPR-mediated knockdown of PDCD1 (which encodes PD1) in CAR-T cells has demonstrated enhanced CAR-T cell performance in both B cell and solid tumor models, resulting in improved in vivo anti-tumor responses." (PMID 37781382, 2023). "The trend of Pdcd1 and Dnmt1 gene upregulations was increasing along with the progression of liver damage from 3 to 12 months of age, representing the natural history of hepatocarcinogenesis from early hepatic damage, inflammation, dysplasia, and finally neoplasia." (PMID 37686163, 2023). "Programmed cell death 1 (PD-1), programmed cell death 1 ligand 1 (PD-L1), cytotoxic T lymphocyte-associated antigen-4 (CTLA-4) and other targets are specifically targeted by ICIs in order to effectively release immunological brake reactions and suppress tumor immune escape." (PMID 37973916, 2023).
tumor (continued). "Inhibitory receptors, such as programmed cell death 1 (PD-1), lymphocyte activation gene-3 (LAG-3), T-cell immunoglobulin-3 (TIM-3), and cytotoxic T-lymphocyte-associated protein 4 (CTLA-4), are highly expressed in tumor-infiltrated CD8+ T cells, which results in CD8+ T-cell exhaustion." (PMID 36945005, 2023). "One of the most successful ICIs targets the programmed cell death 1 (PD‐1) molecule, a key checkpoint on T‐cells which dampens responses (including proliferation, cytokine production and cytotoxicity) when bound to programmed death ligand 1 (PD‐L1) or PD‐L2 on tumour cells." (PMID 36811226, 2023). "Moreover, KLRB1 expression exhibited a positive correlation with the expression of PDCD1 (r = 0.624), CD274 (r = 0.317), and CTLA4 (r = 0.541) under condition of tumor purity, and PDCD1 (r = 0.731), CD274 (r = 0.441), and CTLA4 (r = 0.643) under condition of age in BRCA." (PMID 37988189, 2023). "Immune checkpoint blockade methods targeting cytotoxic-T-lymphocyte-antigen-4 (CTLA-4) or programmed cell death-1 (PD-1)/programmed death-ligand 1 (PD-L1) are currently being pursued by oncologists, because of their ability to treat cancer by restoring T-cell cytotoxicity against tumor cells." (PMID 37228770, 2023). "On the contrary, in vitro and in vivo PDCD1 knockdown models, as well as immunodeficient mice inoculated with lung cancer cell lines and treated with anti-PD-1, showed increased colony expansion and tumor growth, mediated through upregulated AKT and ERK signaling." (PMID 35691988, 2023). "Subsequently, antibodies targeting programmed cell death-1 (PD-1; nivolumab, pembrolizumab, and cemiplimab) or its ligand, programmed cell death ligand-1 (PD-L1; atezolizumab, avelumab, and durvalumab) have also gained approvals and become integrated into the standard-of-care in many tumor types." (PMID 36405729, 2022). "Moreover, the combination therapy of targeting CTLA-4 and PDCD1 could better suppress tumor progression." (PMID 36428756, 2022). "In addition, programmed cell death-1/programmed cell death-ligand 1 (PD-1/PD-L1) is an important immune checkpoint, controlling the induction and maintenance of immune tolerance within the tumor microenvironment." (PMID 36431072, 2022). "S2 was characterized as a ‘cold tumor’ profile with the highest tumor purity score, and S3 as an ‘immunosuppressed tumor’ profile with the poorest prognosis and a high expression level of immunosuppressive genes such as cytotoxic T‐lymphocyte‐associated protein‐4, TIGIT, and PDCD1." (PMID 35124891, 2022). "Moreover, as they can directly and indirectly modulate the expression of programmed cell death 1 (PD-1) and PD-ligand (L) 1 in the tumor environment, targeting of M2-like TAM has been proposed to represent an effective approach in TNBC to modulate the activity of immune checkpoint inhibitors." (PMID 34943901, 2021). "Antibodies that block immune regulatory checkpoints (programmed cell death 1, PD-1 and cytotoxic T-lymphocyte-associated antigen 4, CTLA-4) to mobilise immunity have shown unprecedented clinical efficacy against cancer, demonstrating the importance of antigen-specific tumour recognition." (PMID 33918976, 2021). "However, when looking at the expression level, we observed relatively high expression of LAG3 and HAVCR2 in both primary and recurrent tumor and a trend of greater expression for TIGIT, CTLA4, BTLA, and PDCD1 in recurrent tumor tissue, compared to primary tumor tissue (NS)." (PMID 33352957, 2020). "In addition, SHP2 plays a role in Helicobacter pylori-induced gastric cancer mediated by activation by the bacterial protein CagA17, and SHP2 is responsible for the suppression of T-cell activation by programmed cell death-1 (PD-1), a receptor hijacked by tumor cells for evading the immune response." (PMID 33116231, 2020). "However, tumor cells may suppress immune responses through different mechanisms including the programmed cell death-1 (PD-1)/programmed cell death-ligand 1 (PD-L1) axis." (PMID 32922390, 2020).
tumor (continued). "The tumor inflammation signature (TIS) is comprised of 18 genes and is used to indicate the level of suppression of adaptive immunity in tumors and differentiate response to the checkpoint anti-PD-1 treatment (where PD-1 is encoded in the Programmed Cell Death 1 [PDCD1] gene)." (PMID 32545367, 2020). "Interestingly, we found that ALDH3A2 co-expression might be negatively correlated with the PDCD1, PDCD1LG2, and CTLA4 genes, and positively associated with tumor purity." (PMID 33148208, 2020). "In recent years, immune checkpoint inhibitor (ICI), as represented by the programmed cell death-1 (PD-1) monoclonal antibody, has been shown to have efficacious therapeutic benefit in many solid tumors by restoring the immune function of T-cells to kill tumor cells." (PMID 30886151, 2019). "The interaction between programmed cell death-1 (PD-1), expressed on activated T lymphocytes, and programmed cell death-ligand 1 (PD-L1), expressed on antigen-presenting cells and tumour cells, has a major role in suppression of the anti-tumour immune response." (PMID 31527660, 2019). "We found that 77.4% of the clustered tumor specimens evade through transforming growth factor-beta (TGF-β) immunosuppression, 57.7% through decoy receptor 3 (DcR3) counterattack, 48.0% through cytotoxic T-lymphocyte-associated protein 4 (CTLA4), and 34.3% through programmed cell death-1 (PD-1)." (PMID 30513096, 2018). "Preclinically, combining adenosine receptor inhibition with either chemotherapy or anti-programmed cell death-1 resulted in greater tumor control in mouse models, suggesting that AB928 may have synergistic activity when paired with either chemotherapy or checkpoint inhibitors in oncology patients." (PMID 30400835, 2018). "Preclinically, combining adenosine receptor inhibition with either chemotherapy or anti-programmed cell death-1 resulted in greater tumor control in mouse models, suggesting AB928 may have synergistic activity when paired with either chemotherapy or checkpoint inhibitors in oncology patients." (PMID 30400835, 2018). "One of the most promising targets is the programmed cell death-1 (PD-1) / programmed cell death ligand-1 (PD-L1) checkpoint pathway, which negatively regulates effector T-cell activity, inhibiting antitumor immune responses and thereby promoting tumor immune evasion." (PMID 30041679, 2018). "Therefore, therapies targeting tumor immunogenicity and anti-tumor immunity such as antibodies that inhibit checkpoint molecules, i.e. the programmed cell death ligand-1 (PD-L1)/programmed cell death-1 (PD-1) pathway have recently gained attention as a novel therapeutic option in OC." (PMID 29707124, 2018). "In addition, CD274 promoter methylation significantly correlated with PDCD1 methylation, suggesting that epigenetic regulation of the PD-1 receptor may be paralleled by PD-L1 induction in tumor tissue." (PMID 28487502, 2017). "Finally, we tested whether Pdcd1 disrupted CAR T cells exhibited enhanced anti-tumor efficacy in vivo." (PMID 28389661, 2017). "Programmed cell death protein 1 (PD-1, encoded by PDCD1 gene) and one of its two known ligands, the programmed death ligand-1 (PD-L1, encoded by CD274 gene) are among the therapeutically most important checkpoint proteins that mediate tumor-induced immune suppression through T-cell downregulation." (PMID 27861596, 2016). "Hence, following reduction of the bulk tumour by conventional chemotherapy, blocking the PDCD1 inhibitory pathway might release a ‘brake’ on the T cell receptor signalling and reasonably increase tumour-specific cytotoxicity." (PMID 25940792, 2015). "In addition, we demonstrate that blockade of the PDCD1/CD274 pathway leads to increased tumour cell clearance in the TCL1tg mouse model and might hence represent a promising new option in treatment of this disease." (PMID 25940792, 2015).
tumor (continued). "Importantly, in vitro treatment with rPDCD1 fragment did not affect the viability of mouse tumour cells (Fig4C), implying that in tumour bearing mice, a vast number of tumour-specific exhausted CTLs exist that can be immediately reactivated by PDCD1/PD-L blockage, leading to cytolysis of the tumour." (PMID 25940792, 2015). "The regulation of the programmed cell death protein 1 (PD-1) gene, PDCD1, has been widely explored at transcription and posttranslational levels in T cell function and tumor immune evasion." (PMID 41623183, 2026). "These analyses identified several differentially methylated genes linked to invasiveness (e.g., PHYHD1, WNT4, STAT6, CDH1, CDH13), aggressive behaviour (e.g., AIP, PDCD1, LINE-1), and tumour regrowth (e.g., TERT, FAM90A1, ING2)." (PMID 41866138, 2026). "Within tumor tissues, there was a high enrichment of CD4 Treg, CD8-Tem-PDCD1, CD8-Temra, and CD4 + Tex cells." (PMID 39354287, 2025). "The expression of SIRPA, LILRB1, LILRB2, Siglec1, Siglec7, Siglec9, PDCD1, CD163 and MARCO are preferentially expressed on Mono01, Mono02 and Macro03, suggesting their tumor-promoting roles." (PMID 40755770, 2025). "PSMB9 displayed strong correlations with classical inhibitory molecules such as LAG3, PDCD1, CTLA4, TIGIT, HAVCR2, SLAMF7, and PD-L1 across nearly all tumor types." (PMID 41020834, 2025). "Exhaustion markers including PDCD1, IDO1, and HAVCR2 were predominantly enriched in tumor-adjacent regions, which exhibited partial spatial overlap with ADM expression." (PMID 40547013, 2025). "RCN6 was mainly localized in tumor stroma, where CAF-FAP was spatially proximal to t_MP5, CD8_PDCD1, neutrophil, Monocyte_CD14, and Macrophage_CXCL10, which featured by inflammation and immune exhaustion." (PMID 39870619, 2025). "Upon tumor regrowth, she was treated with the anti-programmed cell death-1 immune checkpoint inhibitor (ICI) pembrolizumab, which resulted in significant tumor reduction." (PMID 40236650, 2025). "Nonresponse to programmed cell death 1 (PD‐1) blockade is associated with a lack of preexisting IFN‐γ–secreting CD8+ T cells in the tumor microenvironment (TME), which suggests that impaired T‐cell priming or trafficking to tumor tissues might be involved in immune resistance." (PMID 40753466, 2025). "CD8+ T cells that exhibited high expression levels of exhaustion gene (HAVCR2, ENTPD1, LAG3, PDCD1, CXCL13, TOX, and GZMB) in the primary tumor were extracted and clustered." (PMID 40364834, 2025). "Especially, a positive correlation between ACAA1 expression in tumor cells and six immune checkpoint-related genes, namely CD27, PDCD1, CD86, BTLA, TIGIT, and CD28, on immune cells within the tumor microenvironment." (PMID 41277949, 2025). "The results revealed that PDCD1/PD-1 and LAG3 exhibited a high level of surface expression on CD8+ T cells in tumor tissues with elevated circGRAMD4 expression." (PMID 40373256, 2025). "This signature includes key genes for maintaining cellular cytotoxicity such as ZNF683,41PRF1, IL2RB, and IFNG and immune activation and exhaustion markers including LAG3, PDCD1, PRF1, and TBX21 that contribute to anti-tumor immunity." (PMID 41045934, 2025). "Recently, immune checkpoint inhibitors targeting programmed cell death 1 and its ligand (PD-1/PD-L1) and Cytotoxic T-lymphocyte antigen-4 (CTLA-4) have shown promising preliminary results in various tumours." (PMID 39941847, 2025). "The selected biomarkers (EGFR, ALK, KRAS, and PDCD1), demonstrated significantly higher expression in NSCLC tumor tissues compared to adjacent normal tissues (p < 0.01)." (PMID 40927719, 2025). "Research in the past has established that the overexpression of PDCD1 leads to the persistence and progression of CLL through the suppression of T-cells in the tumor microenvironment." (PMID 41249728, 2025).